GZMB (granzyme B)
Diseases named in the same sentence as GZMB in open-access papers (continued):
Sharing a sentence is not in itself a finding about the gene and the disease.
tumor (continued). "Additionally, analysis of CD8+ T cells revealed that Fgl2 knockout elevated the number of tumor-infiltrated CD8+ T cells and their production of granzyme B in DLNs." (PMID 31409352, 2019). "This indicated that cytolytic activity, such as perforin and granzyme B release, was not involved in the anti-tumor effects." (PMID 31105882, 2019). "Mock T cells remained “quiescent” with minimal release of IFN-γ and Granzyme B because there was no stimulatory signal between the tumor cells and mock T cells (top)." (PMID 31178870, 2019). "Notably, HPK1 KD mice showed markedly increased pro-inflammatory pathways in response to priming with tumor antigens as shown by the enhanced related gene expression, e.g. S100A8, GZMB, NKp44, CXCL14, CX3CL1, CD1d2, KLRG1, CD11c, NLRP3 and MUC1." (PMID 30913212, 2019). "Likewise, we found, in B16F10 tumours, that a significant percentage of Nrp-1+PD-1hi CD8+ TIL strongly expressed granzyme B and cell proliferation marker Ki-67, and secreted high levels of IFNγ." (PMID 31350404, 2019). "Following TfR-BiTE-mediated tumor lysis, both CD8 and CD4 T-cell subsets maintained an activated phenotype as shown by expression of the early activation marker CD69 and cytotoxic granule granzyme B (GrB)." (PMID 31293575, 2019). "Further evidence that IR-780 induced a more pronounced effector phenotype was attained by the assessment of multiple CTL effector markers through real-time qPCR of the whole tumor mRNA, demonstrating increased expression of IFN-γ, TNF-α, Granzyme B, EOMES, Perforin, BLIMP-1, FOXO3, and CXCL10." (PMID 31781498, 2019). "Tumor samples from HPK1 KD mice demonstrated significantly upregulated key immune cell markers involved in mediating anti-tumor immunity, including CD4, CD8, IFNγ, TNFα, Granzyme B, CD28, CD11c and CD11b." (PMID 30913212, 2019). "CAR-T cells were then added to antigen-positive and antigen-negative tumor cell lines at the same or lower oxygen level and characterized for cytotoxicity, cytokine and granzyme B secretion, and PD-1 upregulation." (PMID 31052261, 2019). "This combination treatment was associated with an increase in tumor-infiltrating CD8+ T cells and granzyme B staining without changes in NK cells." (PMID 31412566, 2019). "When reactivated by T-cell receptor (TCR) activator, tumor-infiltrating NKG2A+ CD8+ T cells increased the secretion of granzyme B, even with just a weak stimulus, but not IFN-γ." (PMID 32010126, 2019). "Moreover, tumor infiltrating CD8+ T cells from STING agonist treated mice were increasingly proliferative and activated, as determined by Ki-67+ and granzyme B+ expression." (PMID 31036082, 2019). "In the immunological synapse formed between tumor cells and effector cells, effector cells (CTL or activated NK cells) expressing GzmB have high cytotoxic activity against tumor cells, but those expressing GzmA) do not." (PMID 31293597, 2019). "IL-35 stimulation only reduced granzyme B mRNA expression in liver-resident CD8+ T cells from tumor site (paired t-test, P = 0.031), however, did not affect FasL mRNA expression (paired t-tests, all P > 0.05)." (PMID 31134088, 2019). "Importantly, reduced release of granzyme B by γδ T cells cocultured with TRAIL-R4-KD cells was partially reverted by bispecific antibody [HER2xCD3] and led in consequence to enhanced lysis of tumor cells." (PMID 31555275, 2019). "We harvested fresh NK cells from non-tumor bearing wild type C57BL/6 mice and treated them with NextA in vitro to investigate the reported markers for NK cell activity and cytotoxicity, such as Granzyme B, TRAIL, and Fas ligand." (PMID 30992475, 2019). "However, they can recognize the tumor-antigen-MHC-I-complex in the presence of antigen presenting cells (APCs), and thereby destroy tumor cells through the perforin-granzyme B- and/or Fas-Fas ligand axis-mediated apoptosis." (PMID 30823602, 2019).
tumor (continued). "The sole administration of naked poly A:U promotes striking changes within the lymphoid compartment, with all the anti-tumoral parameters being enhanced: a higher frequency of CD8+ Granzyme B+ T cells, (lower Treg/CD8+ ratio) and an important expansion of tumor-antigen specific CD8+ T cells." (PMID 30949170, 2019). "Also correlating were GZMB and FASLG, both necessary for anti-tumor CD8 T cell cytotoxic functionality, PD-1 and LAG3, representing T cell activation and exhaustion, and TAP2, necessary in MHC I antigen presentation." (PMID 29487705, 2018). "Granzyme B protein levels were subsequently assayed by ELISA and, in corroboration of the gene expression data, were increased in the lungs of QBKPN-administered tumor-bearing mice relative to placebo." (PMID 29399400, 2018). "Maximal tumour shrinkage coincided with a decreased Ki67 proliferative index, increases in tumour CD8+ cytotoxic T cells, FoxP3+ Tregs, and NK cells, as well as higher granzyme B staining and IFNγ production, confirming increased cytotoxicity." (PMID 30327563, 2018). "In our effort to characterize the signaling pathways involved in the expression of GZMB in neutrophils, we also showed that GZMB was expressed in tumor-infiltrating neutrophils but not in neutrophils from spleen." (PMID 29983866, 2018). "Our data also showed that GZMB+-neutrophils have anti-tumor activity when activated by a TLR4 agonist unlike those devoid of GZMB, and their infiltration into tumor probably contributed to the LipA-mediated tumor cell death." (PMID 29983866, 2018). "However, despite complete coverage of GITR by AMG 228 in peripheral blood and in tumor biopsies and a decrease in blood GITR+ Treg numbers following treatment, little evidence of immune modulation (ie, T cell activation and granzyme B activation) was observed." (PMID 30253804, 2018). "In addition, a limited number of T cells (CD3+) was present in the tumor microenvironment, with a higher number of regulatory T cells (Foxp3+) and macrophages (CD11b+) as compared to activated cytotoxic T cells (CD8+/ Granzyme B+)." (PMID 30458852, 2018). "Furthermore, in the tumor draining lymph node we observed ibuprofen to reduce Rorgt+ CD4+ T cells and restore Granzyme B+ expression in T cells suppressed by the involution environment." (PMID 30285905, 2018). "Consistent with the RNA-sequencing and RT-PCR results, Chi3l1 KO mice had increased mRNA for anti-tumor immunity molecules including CTSE, TRAL, IFNγ, T-bet, Perforin, and Granzyme B, while the expression of Th1-inhibitory molecules such as Twist1 and SOCS1 was significantly reduced." (PMID 29403003, 2018). "In the first case, tumour cells are negative for granzyme B and perforin but they express weakly TIA-1." (PMID 30151671, 2018). "Since tumour-infiltrating lymphocytes are the main effectors of immune-cell mediated death, immunohistochemistry was performed for the CD8+ T cell subset, granzyme B, a serine protease and marker of cytotoxicity of lymphocytes, and FoxP3, a putative marker of Tregs." (PMID 30327563, 2018). "Emerging STAT3-null tumours re-established immune suppression based on the absence of a robust Granzyme B+ response and impaired nuclear STAT1 translocation." (PMID 28276425, 2017). "We assessed whether the granzyme B (GrB) and interferon-y (IFN-y) secretion correlated with the observed tumor cell lysis observed in vitro." (PMID 28415565, 2017). "Furthermore, it has been reported that IMQ induces the expression of Granzyme B and TRAIL on pDCs sufficiently to effectively lyse appropriate tumor targets." (PMID 28052019, 2017). "In support of this hypothesis, phenotypic characterization of the tumour-infiltrating CD8+ cells from both treated and distant tumours revealed a more robust upregulation of the markers indicative of effector function (that is, ICOS and Granzyme B)." (PMID 28194010, 2017).
tumor (continued). "We detected a statistically significant increase in mRNA levels of IFN-γ, granzyme B, TNF-α and perforin 1 in CD8+ TIL from Grail−/− mice, further supporting that Grail controls the effector function of CTLs infiltrated into the tumours." (PMID 28798332, 2017). "In both treated tumours and the spleen, NDV-ICOSL/anti-CTLA-4 treatment resulted in the highest increase in the percentages of CD8+ cells characterized by high expression of Granzyme B and ICOS." (PMID 28194010, 2017). "Researches have demonstrated that CD4+ CD25+ Foxp3+ Tregs inhibited proliferation, activation, degranulation, and production of granzyme A, granzyme B, and perforin of CD8+ T cells induced by anti-CD3/CD28 antibodies and are potent suppressors of autologous tumor-specific T cell responses." (PMID 28399886, 2017). "Finally, tumor cells talked to NK cells through CYR61-ITGAM and CYR61-ITGA5 and NK cells talked back through GZMB-PGRMC1." (PMID 28821810, 2017). "We observed that IFNγ and granzyme-B expression on Vβ8.1/2+CD8+T cells in the spleens of tumor-bearing mice injected with IL-12 and IL-15 neutralization antibodies was significantly reduced compared with the expression in unneutralized tumor-bearing mice." (PMID 28052005, 2017). "Tumor cells talked to macrophages through the ligand receptor pairs C1QB-LRP1, COL1A2-LRP1 and SERPINE2-LRP1, and macrophages talked back through SERPINA-LRP1, C1QB-LRP1 and C1QA-CSPG4; tumor cells talked to T-cells through COL1A2-ITGA1 and T cells talked back through GZMB-PGRMC1." (PMID 28821810, 2017). "Cx43-GJICs among NK cells and tumor cells appear to not affect tumor-induced NK cell degranulation but instead do control the NK cell cytotoxicity by contributing to granzyme-b activity and Ca2+ influx into tumor cells." (PMID 28919895, 2017). "Based on these data, an important issue arises from these results: Is GZMB selectively degraded by autophagy or is it just an “innocent victim” which is subject to a bulk nonspecific degradation in hypoxic tumor cells under excessive autophagy?" (PMID 26910842, 2016). "Additionally, to estimate immune cell prevalence we used the average expression of the lymphocyte-specific genes GZMB, PRF1, CXCL13, IRF1, IKZF1, and HLA-E in each tumor sample." (PMID 27959926, 2016). "Although reliant on perforins in natural attacks, granzyme B can also effectively kill tumor cells in the absence of perforin when targeted to cell surface receptors." (PMID 27376327, 2016). "Tumor protection was also associated with differentiation of CD4+ and CD8+T-subpopulations and NK1.1+activation as measured by granzyme B expression, not detected in the control conditions at day 35 after tumor challenge." (PMID 26405163, 2015). "At euthanasia, the C-ter-J28+-mDC-vaccinated recipients challenged with Panc02 displayed high expansion of CD4+- and CD8+-T-cells expressing granzyme B (more than 44%) in spleen compared to mDC-recipients (less than 10%) and a PBS-control mouse with late tumor development (2.5%) (5C)." (PMID 26405163, 2015). "Furthermore, tumor cells pre-incubated with Ara-C stimulated more perforin (MFI: CD8+: 28.24 ± 1.18, CD4+: 16.77 ± 1.35) and granzyme B (MFI: CD8+: 35.47 ± 1.20, CD4+: 22.30 ± 0.40) than tumor cells alone." (PMID 26444983, 2015). "Tumor cell-induced granzyme B secretion and cytotoxicity were also completely absent in TRPM2−/− NK cells." (PMID 25879940, 2015). "On the other hand, NAC did significantly increase the % of granzyme B+/perforin+ NK cells, irrespective of the tumour response to NAC." (PMID 26040463, 2015). "Tumor-infiltrating Th17 cells expressed high CD45RO, HLA-DR, but low granzyme B and PD-1." (PMID 25768730, 2015). "Human BNIP-2 was found to be directly processed at IEAD28 by granzyme B in vitro and during natural killer cell-mediated killing of tumor cells and thus not secondary to granzyme B induced caspase activation." (PMID 25208769, 2014).
tumor (continued). "The scFvMTBHsp70/tumor cell-pulsed DCs induced significantly higher production of IFN-γ and Granzyme B from both CD4+ and CD8+ tumor cell-primed T cells as compared with MTBHsp70 or PBS, indicating that scFvMTBHsp70 enhances tumor antigen presentation and cross-presentation by DCs." (PMID 24565018, 2014). "In mice lacking Tregs, the frequency of GzmB-positive cells was significantly higher compared to non-depleted tumor-bearing mice." (PMID 22890822, 2013). "Presentation of tumor-specific antigens by antigen-presenting cells to CD8+ T cells results in release of different cytotoxic molecules (e.g., perforin, granzyme A, granzyme B, TNF-related apoptosis-inducing ligand (TRAIL), Fas ligand) which can target and kill dysplastic and tumor cells." (PMID 23109839, 2012). "However, higher frequencies of CD8+Granzyme B+ cells, presumably differentiated CTL, were present in the tumor than the unaffected tissue." (PMID 22319577, 2012). "Only a very small fraction of CD8+ splenocytes isolated from unimmunized control mice expressed granzyme B, while 25.6% of CD8+ splenocytes from vaccinated/tumor challenged mice expressed this CTL effector (n = 6/group; t test, p<0.05; relative to control group)." (PMID 22860107, 2012). "On the other hand, the presence of putative cytotoxic Granzyme B+CD8+ T cells was increased in the tumor, and these cells may be a sign of ongoing anti-tumor responses." (PMID 22319577, 2012). "In addition, vinblastine pretreatment also limitedly reduced the percentage of CCR6−Tregs in tumor mass (p>0.05) and led to slightly elevated IFN-γ production and proliferation, as well as the expression of CD107a and Granzyme B, of CD8+T cells (p>0.05)." (PMID 21655250, 2011). "Indeed, we observed greater percentages of granzyme B-and FasL-expressing CD8+ T cells after co-culture of tumours, T cells and MEDI-565 when compared with control-BiTE." (PMID 19953093, 2010). "In high-grade serous tumors from optimally debulked patients, positive associations were seen between intraepithelial cells expressing CD3, CD4, CD8, CD45RO, CD25, TIA-1, Granzyme B, FoxP3, CD20, and CD68, as well as expression of MHC class I and II by tumor cells." (PMID 19641607, 2009). "In fact granzyme B has not been shown to be expressed in naive Treg cells but it is highly expressed in 5%–30% of Tregs in the tumor environment." (PMID 20169125, 2009). "We show here that Vβ6+ T cells kill vSAG7+ tumour cells via release of perforin and granzyme B. Interestingly, this form of cell death is independent of the known caspases and occurs without the involvement of mitochondria." (PMID 11875749, 2002). "In conclusion, we show that vSAG7 specific T cells rapidly induce apoptosis in vSAG7+ tumour cells via perforin and granzyme B which occurs without involvement of mitochondria and independently of caspases." (PMID 11875749, 2002). "Responders (CR/PR) exhibited robust cytotoxic T-cell activation characterized by up-regulation of GNLY, GZMB, and CXCL13, whereas non-responders (SD) uniquely showed persistent overexpression of HSPA1B, a stress-response gene associated with tumor progression and immune suppression." (PMID 42158872, 2026). "Furthermore, the marked increase in IFN-γ and granzyme B secretion by splenocytes from MNEV-immunized mice underscores the vaccine’s capacity to stimulate cytotoxic T-cell activity, a critical mechanism for tumor cell elimination." (PMID 40453095, 2025). "Notably, in the absence of CD8+ T cells, Treg-derived GZMB still enhanced lung metastasis in these models, indicating its ability to promote tumor metastasis independently of cytotoxic T cells." (PMID 41567188, 2025). "Although multiple granzyme genes in CD8+ TIL were increased with IL-15 complexes and anti-PD-1 treatment and correlated with the overall influx of CD8+ T cells within the tumor parenchyma, the gene expression of granzyme B was not increased as determined using Nanostring®." (PMID 41373645, 2025).
tumor (continued). "Additionally, the production of effector molecules by tumor-infiltrating CD8+ T cells, including IFN-γ and GzmB, was remarkably increased following DS and anti-PD-1 antibody combination treatment, further supporting the activation of cDC1s and cytotoxic CD8+ T cells." (PMID 40625660, 2025). "Interestingly, immune checkpoints on CD8+ T cells were downregulated with selinexor at the tumour site, and although not significant, granzyme B and IFNγ expression were increased, highlighting an active immune response within the TME with selinexor." (PMID 40291981, 2025). "The significant Increase in the expression of genes such as GZMB (granzyme B) and GNLY (granulysin) in CD8+ T cells of patients unresponsive to anti-PD1 treatment could reflect an attempt by the immune system to fight the tumor through the activation of CD8+ T cells." (PMID 40182035, 2025). "Consequently, this paper aims to summarize the role of GZMB’s non-classical pathways in tumor initiation and progression, thereby enhancing our understanding of its intricate mechanisms." (PMID 41567188, 2025). "Upon antigen recognition, CTLs execute their cytotoxic functions by secreting granzyme B and perforin, increasing the synthesis and release of cytokines such as interferon-gamma (IFN-γ) and tumor necrosis factor-alpha (TNF-α) and inducing tumor cell apoptosis via the FasL/Fas pathway." (PMID 40458394, 2025). "DAC/IL-33 and PD-1 mAb strongly synergized to increase tumor-infiltrating immune effector cells (i.e., CD4 T cells, CD8 T cells and eosinophils) and intratumoral expression of effector molecules (i.e., IFN-γ, granzyme B, perforin and TNF-α) which may account for therapeutic efficacy." (PMID 40317004, 2025). "Investigate the antitumor mechanism, western blot analysis was performed on tumor tissues to assess the expression of cleaved caspase-3, PD-1, and granzyme B. Both TCV and TCV-BAM15 treatments induced the expression of caspase-3 and granzyme B, with TCV-BAM15 showing the most robust effect." (PMID 40595481, 2025). "Additionally, these MoDCs increased the frequency of CD4+Granzyme B+ cells, a subset of cytotoxic CD4+ T cells that may enhance anti-tumor immunity." (PMID 40574085, 2025). "The decreased numbers of CD8+ and GZMB+ cells were observed in OG‐L002‐treated and NC group in Model 2 compared to those in Model 1, indicating that the recurrent xenografts exhibited the impaired effector T cell ability in TME compared with the original tumour." (PMID 40356247, 2025). "Interestingly, high expression of GZMA, GZMB, IFNG, and PRF1 in exhausted T-cells may be attributed to feedback responses due to complex interactions with other stromal cells in the tumor microenvironment (TME)." (PMID 40236693, 2025). "Focusing on T- cell and tumor cell states within different neighborhoods, in the Fibroblast-Enriched neighborhood, T- cells presented downregulation of activation markers, including CD44, CD45RO, HLA-A, ICOS, and Granzyme B, suggesting that fibroblasts play an immunosuppressive role." (PMID 41254766, 2025). "Cytokine analysis of tumor tissues revealed that the combination of Liensinine and immunotherapy significantly elevated levels of pro-inflammatory cytokines, including TNF-α, IL-12, IFN-γ, and granzyme B, while reducing the levels of immunosuppressive cytokines, such as IL-10 and TGF-β." (PMID 40665352, 2025). "The system effectively expands tumor-infiltrating lymphocytes, resulting in a 6.62-fold increase in CD4+ T cells compared to controls, along with elevated populations of CD8+ T cells and Granzyme B+ cytotoxic cells, as well as enhanced pro-inflammatory cytokine expression." (PMID 41267084, 2025). "While our study did not include direct phenotypic characterization of tumor-infiltrating CD8+ T cells for markers such as granzyme B, IFN-γ, PD-1, or exhaustion profiles, functional data from in vivo CTL assays and ELISPOT suggest that these T cells were actively involved in cytotoxic responses." (PMID 40943370, 2025).